TFPI2 (tissue factor pathway inhibitor 2)
Diseases named in the same sentence as TFPI2 in open-access papers (continued):
Sharing a sentence is not in itself a finding about the gene and the disease.
squamous cell carcinoma (2 papers, 2005 to 2020). A carcinoma arising from squamous epithelial cells. "Squamous cell cancer proximal to the cervical surface as well as in the tumor stroma expressed small amounts of cytoplasmic TFPI-2." (PMID 32559232, 2020). "This downregulation of TFPI-2 gene was observed in both adenocarcinomas (11/35, 31%) and squamous cell carcinomas (9/16, 56%)." (PMID 15685245, 2005).
Thromboembolism (2 papers, 2022 to 2023). The formation of a blood clot inside a blood vessel that subsequently travels through the blood stream from the site where it formed to another location in the body, generally leading to vascular occlusion at the distant site. "On the other hand, clinical biomarker candidates associated with hypercoagulation statuses such as serum TFPI2, thromboembolism, plasma D-dimer, and plasma IL6 should also be evaluated for changes over time." (PMID 35565252, 2022). "Recent studies have shown that decreased TFPI1 levels or increased TFPI2 levels are associated with an increased risk of thromboembolism in cancer patients, suggesting that TFPI1 and TFPI2 may exhibit different biological activities." (PMID 37238908, 2023).
acute myeloid leukemia (1 paper, 2014). Acute myeloid leukemia (AML) is a group of neoplasms arising from precursor cells committed to the myeloid cell-line differentiation. "No studies report TFPI-2 methylation in human lymphoma, although this phenomenon is described in pediatric acute myeloid leukemia." (PMID 24695110, 2014). "Epigenetic dysregulation of TFPI-2, leading to its reduced expression, has been observed in pediatric acute myeloid leukemia, while no information is available for lymphoma." (PMID 24695110, 2014).
aging (1 paper, 2025). A developmental process that is a deterioration and loss of function over time. "In the context of skin aging, TFPI2 downregulation contributes to senescence by impeding cellular proliferation through the PI3K/Akt/CDC6 axis." (PMID 40361374, 2025).
benign breast tumors (1 paper, 2013). "Almost all benign breast tumors exhibited high levels of TFPI-2 expression, with a mean of mean-density of TFPI-2 staining as 0.697 (95% CI 0.662-0.732)." (PMID 23497249, 2013).
Cerebral ischemia (1 paper, 2025). Restriction of arterial blood supply to the brain associated with insufficient oxygenation to support the metabolic requirements of the tissue. "AP-1 also upregulates TFPI2 during ovulation, and its inhibition in cerebral ischemia/reperfusion injury restores blood-brain barrier integrity, indicating AP-1–mediated TFPI2 elevation." (PMID 40361374, 2025).
cross-infection (1 paper, 2021). "As a non-invasive detection method, SDC2/TFPI2-joined detection in stool samples is safe and can be operated easily, avoiding bowel preparation and possible cross-infection during colonoscopy." (PMID 35004840, 2021).
cutaneous melanoma (1 paper, 2021). A primary melanoma arising from atypical melanocytes in the skin. "High levels of TFPI2 were correlated with worse and better survival in uveal and cutaneous melanoma, respectively." (PMID 34249699, 2021). "Data from The Cancer Genome Atlas (TCGA) were analyzed to explore the expression and prognostic implications of TFPI2 in uveal and cutaneous melanoma." (PMID 34249699, 2021).
cystic fibrosis (1 paper, 2018). Autosomal recessive disorder caused by pathogenic variants in the CFTR gene (cystic fibrosis transmembrane conductance regulator), which encodes a chloride and bicarbonate channel expressed in epithelial cells, and follow the diagnosis criteria. "Moreover, in sputum from cystic fibrosis patients TFPI-2 C-terminal fragments are generated and found associated with immunoglobulins." (PMID 30254643, 2018).
E. coli infection (1 paper, 2018). "In order to explore the function of TFPI-2 during systemic inflammation we analyzed the expression levels of TFPI-2 in two relevant animal models, a murine endotoxin-induced model and an E. coli infection model." (PMID 30254643, 2018).
fatty liver (1 paper, 2024). "HOPE alleviated the inflammatory response in fatty liver IRI by inhibiting TFPI2 expression, which mainly involves regulating the TLR4/NF-κB inflammatory signaling pathways." (PMID 39617791, 2024). "We transfected AAV8 constructs overexpressing or knocking down TFPI2 expression in rats fed an MCD diet to analyze the role of TFPI2 during fatty liver IRI." (PMID 39617791, 2024). "Overall, we found that HOPE plays an important role in alleviating fatty liver IRI by regulating the TFPI2/CLIP1/TIRAP pathway to suppress the inflammatory response in a rat model of severe fatty liver." (PMID 39617791, 2024). "Therefore, our findings suggest that targeting the TFPI2/CLIP1/TIRAP signaling pathway with HOPE could be a potential therapeutic strategy for alleviated IRI in fatty liver transplantation." (PMID 39617791, 2024). "We obtained samples from five cases of nonfatty liver and five cases of fatty liver from clinically discarded livers, all of which underwent 8–24 h of CS before collection to confirm the changes in TFPI2 and CLIP1 molecules in human fatty liver." (PMID 39617791, 2024). "However, the underlying mechanisms of HOPE in fatty liver and the effects of TFPI2 and CLIP1 in fatty liver IRI remain unclear." (PMID 39617791, 2024).
glaucoma (1 paper, 2009). Increased pressure in the eyeball due to obstruction of the outflow of aqueous humor. "Therefore, the aim of the present study was to elucidate the effect of TFPI-2 on hTCF proliferation and migration to determine its suitability as an antiscarring agent for in vivo use after glaucoma filtration surgery." (PMID 19936309, 2009). "Its ability to inhibit cell motility may render TFPI-2 a promising candidate for novel therapies for preventing or reducing unwanted wound-healing scars after glaucoma drainage surgery." (PMID 19936309, 2009). "The aim of the study is to elucidate the effect of TFPI-2 overexpression on hTCF proliferation and migration, to determine whether TFPI-2 may act as an antiscarring agent in vivo after glaucoma filtration surgery." (PMID 19936309, 2009). "Human tissue factor pathway inhibitor-2 (TFPI-2), an inhibitor of MMPs, may inhibit scarring after glaucoma filtration surgery." (PMID 19936309, 2009). "TFPI-2 expression may strongly inhibit the migration ability of hTCFs in vitro, making it a promising candidate for novel therapies to minimize scar development after glaucoma drainage surgery." (PMID 19936309, 2009).
human papillomavirus infection (1 paper, 2021). "Specifically, in UM, TFPI2 coexpression genes are mainly associated with pathways of human papillomavirus infection and calcium signaling, while in CM, TFPI2 coexpression genes are mainly associated with cytokine–cytokine receptor interaction and TNF signaling pathways." (PMID 34249699, 2021).
hypercoagulable (1 paper, 2023). "Therefore, TFPI2 produced by the syncytiotrophoblasts would provide antifibrinolytic activity and stabilize clotting factors during pregnancy and delivery to maintain a hypercoagulable state and inhibit bleeding." (PMID 37238908, 2023).
Lassa fever (1 paper, 2021). A viral hemorrhagic fever that is caused by the Lassa virus, which is transmitted by contact with infected rodents; it is characterized by fever, headache, malaise, myalgia, and hearing loss. "Genes involved in extracellular matrix and cell-adhesion were also modulated, particularly during fatal Lassa fever (NID1, TIMP3, ITGA11, TGM2, MMP8/9, OLFM4, PCDH20, and CADM3), as well as some others involved in coagulation (SERPIN, TFPI2) and apoptosis (CLU, BCL2L14)." (PMID 33398113, 2021).
lymphoma (1 paper, 2014). A malignant (clonal) proliferation of B- lymphocytes or T- lymphocytes which involves the lymph nodes, bone marrow and/or extranodal sites. "Further analysis will consider a set of canine lymphoma cell lines to test the efficacy of hypomethylating agents and a larger number of cases to assess whether TFPI-2 promoter hypermethylation may be considered in association with prognosis and therapy." (PMID 24695110, 2014). "Although TFPI-2 transcriptional silencing, through promoter hypermethylation, has been widely reported in several human malignancies, it has never been explored in lymphoma." (PMID 24695110, 2014).
myocardial ischemia (1 paper, 2025). A disorder of cardiac function caused by insufficient blood flow to the muscle tissue of the heart. "miR-23a inhibition protects against myocardial ischemia/reperfusion injury by upregulating TFPI2 following luteolin (a natural flavonoid) treatment." (PMID 40361374, 2025).
neuroblastoma (1 paper, 2025). Neuroblastoma (NB) is the most common solid, extracranial childhood tumor. "These cytokines influence vascular remodeling and angiogenesis and can restore TFPI2 expression, reducing neuroblastoma proliferation and invasion." (PMID 40361374, 2025). "MYCN pro-to-oncogene (MYCN) suppresses TFPI2 and promotes tumor invasiveness, while TGFBI counteracts this by restoring TFPI2 expression in neuroblastoma." (PMID 40361374, 2025).
oligodendroglioma (1 paper, 2021). A well-differentiated (WHO grade II), diffusely infiltrating neuroglial tumor, typically located in the cerebral hemispheres. "A similar expression of TFPI-2 antigens was observed in the tissues of G2 and G3 oligodendrogliomas." (PMID 33947134, 2021).
oral cancer (1 paper, 2014). "The level of TFPI-2 methylation was also found to differ between preoperative and postoperative saliva DNA in oral cancer patients, highlighting its potential diagnostic value as a biomarker for oral cancer." (PMID 25179542, 2014).
ovarian diseases (1 paper, 2016). "The area under the ROC curve (AUC) of serum TFPI2 was obviously higher than that of CA125 for discrimination of CCC from other ovarian diseases (AUC = 0.891 versus 0.595)." (PMID 27798689, 2016). "Also, in a subset of samples of the validation set (20 patients with ovarian diseases and 13 patients with Ut diseases), we compared serum levels of TFPI2 with days from the last menstrual period at the time of sample collection." (PMID 27798689, 2016). "Our data showed that serum TFPI2 is a good biomarker for discriminating ovarian CCC from other ovarian diseases, but further investigation is needed to determine whether TFPI2 can distinguish between ovarian CCC and cancers in other tissues." (PMID 27798689, 2016). "The ROC analysis revealed that TFPI2 was obviously superior to CA125 in discrimination of CCC patients from patients with other ovarian diseases (AUC = 0.891 versus 0.595), borderline ovarian tumors and non-CCC EOCs (AUC = 0.856 versus 0.639), and EMS, respectively (AUC = 0.920 versus 0.700)." (PMID 27798689, 2016). "Furthermore, TFPI2 could almost completely discriminate patients with late-stage CCC from those with other ovarian diseases (AUC = 0.987), borderline ovarian tumors and other EOCs (AUC = 0.981), or EMS (AUC = 0.997)." (PMID 27798689, 2016). "AUC values also indicated that TFPI2 was superior to CA125 in discriminating CCC patients from patients with other ovarian diseases (AUC = 0.817 versus 0.785), BD and non-CCC EOCs (AUC = 0.797 versus 0.708), or EMS (AUC = 0.807 versus 0.803)." (PMID 27798689, 2016).
pterygium (1 paper, 2022). A wedge-shaped fibrovascular lesion arising from the bulbar conjunctiva and extending to the cornea. "TFPI2 encodes an inhibitory protein that inhibits plasmin, trypsin and other serine proteases, possibly playing a role in pterygium pathogenesis once it is involved in extracellular matrix modulation." (PMID 34997134, 2022).
serous carcinoma (1 paper, 2021). "Four patients with advanced high grade serous carcinoma manifestation massive pleural and/or ascites showed very high levels of TFPI2 (1018–7649 pg/mL) together with high CA125 (380–16,587 U/mL)." (PMID 34009487, 2021).
uterine disease (1 paper, 2016). "Serum TFPI2 levels were measured in serum samples from a retrospective training set consisting of patients with benign and borderline ovarian tumors, EOC subtypes, and uterine diseases." (PMID 27798689, 2016).
viral infection (1 paper, 2022). "Several studies had reported that bacterial or viral infection could induce TFPI-2 expression in different tissues." (PMID 35736157, 2022).
tumor (112 papers, 2005 to 2026). "Tfpi2 is recognized as an important tumor suppressor associated with extracellular matrix (ECM) modulation and plays a critical role in tumor invasion and metastasis as well as proliferation, adhesion and apoptosis." (PMID 39859313, 2025). "Not only was it found that hypermethylation of the TFPI-2 gene occurred exclusively in tumor cells, but levels of TFPI-2 mRNA were also markedly reduced in tumor-associated fibroblasts, despite the TFPI-2 gene being unmethylated." (PMID 39153052, 2024). "Overexpression of this validated TFPI2-targeting miRNA in OC tissue has been associated with tumour cell proliferation, invasion, migration and chemoresistance, as well as a poor PFS." (PMID 39199316, 2024). "Reduced synthesis of TFPI2 has been associated with angiogenesis, inflammation, atherosclerosis and tumour growth and metastasis." (PMID 37569483, 2023). "Specifically, TFPI2AS1 is upregulated and inhibits tumour cell proliferation and metastasis by upregulating TFPI2 expression, although the underlying mechanisms are unclear." (PMID 37569483, 2023). "While complex context-dependent effects exist, TF exhibits many tumor-promoting properties, whereas its natural inhibitors TFPI-1 and TFPI-2 have been associated with tumor suppressor activity." (PMID 36900315, 2023). "TFPI2 (tissue factor pathway inhibitor-2) is a tumor-suppressor gene that induces apoptosis, but hypermethylated TFPI2 is associated with several human cancers and dysregulated TFPI2 overexpression promotes EMT through the TGF-β pathway." (PMID 36980828, 2023). "In the present work, we investigated the mechanism of TFPI2 downregulation in tumor-associated fibroblasts and tumor cells." (PMID 32559232, 2020). "As miR-23a-3p influenced mostly TFPI-2 protein expression in normal fibroblast cells, these results indicated that miR-23a-3p is a possible key factor in the inhibition of TFPI2 translation in tumor-associated fibroblasts." (PMID 32559232, 2020). "Five miRNAs (miR-616, miR-646, miR-554, miR-3529-5p and miR-23a) were predicted in silico to inhibit TFPI2 translation in tumor-associated fibroblast based on different miR databases." (PMID 32559232, 2020). "In vivo subcutaneous xenotransplanted tumor model was established to detect tumorigenic function of TFPI2, and the underlying mechanism was evaluated by immunohistochemistry and western blot." (PMID 32248791, 2020). "This indicated that, in addition to that of their own protein, cancer cells are capable to downregulate TFPI-2 production in tumor and metastasis-associated fibroblasts." (PMID 32559232, 2020). "This implies that the E6/E7 oncoproteins hinder the expression of miR-23a-3p, which, as a consequence, cannot exert its TFPI-2 inhibitory effect in HPV infected cells but is capable of downregulating TFPI-2 in virus-free tumor-associated fibroblasts." (PMID 32559232, 2020). "It has been reported that in a number of tumor cell lines, exogenous application of recombinant TFPI-2 (rTFPI-2) in conditioned medium caused rTFPI-2 to be rapidly internalized by the cells and distributed in both the cytosolic and nuclear fractions." (PMID 29051606, 2017). "Tissue factor pathway inhibitor-2 (TFPI-2) expression is downregulated in a variety of tumors, and is associated with tumor invasion and metastasis." (PMID 24396436, 2014). "The loss of TFPI-2 expression is a key event for oral tumorigenesis, especially in the process of tumor metastasis." (PMID 25179542, 2014). "Our previous studies, along with the reports by others, indicate that dysregulation of TFPI-2 is associated with tumor progression." (PMID 23497249, 2013). "The levels of the aberrantly-spliced variant of TFPI-2 were either very low or undetectable in normal tissue, but markedly upregulated in tumor tissues and several tumor cell lines." (PMID 17352822, 2007).